FETUB (fetuin B)
Description:
Protease inhibitor required for egg fertilization. Required to prevent premature zona pellucida hardening before fertilization, probably by inhibiting the protease activity of ASTL, a protease that mediates the cleavage of ZP2 and triggers zona pellucida hardening (By similarity).
Synonyms: 16G2; Gugu; IRL685
Tractability: Antibody: UniProt places it where antibodies can reach, with medium confidence; UniProt predicts a signal peptide or a membrane-spanning region; its Gene Ontology location is reachable by antibodies, with medium confidence. PROTAC: its protein half-life has been measured.
Gene: Protein-coding gene on chromosome 3 (186,634,558 to 186,653,778, forward strand). Ensembl gene ENSG00000090512.
Subcellular location: Secreted
Subcellular location (Human Protein Atlas): Vesicles; Predicted to be secreted
Gene Ontology:
Molecular function: protein binding; metalloendopeptidase inhibitor activity; cysteine-type endopeptidase inhibitor activity
Biological process: binding of sperm to zona pellucida; negative regulation of endopeptidase activity; single fertilization
Cellular component: extracellular exosome; extracellular region
Genetic constraint (gnomAD): Loss-of-function variants: 12 observed, 16.35 expected, observed/expected ratio (o/e) 0.73, 90% interval 0.47 to 1.19. The upper end of that interval is the gene's LOEUF score, 1.19, which puts it in group 5 of 6, group 1 being the genes least tolerant of losing a copy. Missense variants: 366 observed, 377.02 expected, observed/expected ratio (o/e) 0.97, 90% interval 0.89 to 1.06. Synonymous variants: 163 observed, 153.89 expected, observed/expected ratio (o/e) 1.06, 90% interval 0.93 to 1.21.
Homologues: Orthologues: chimpanzee FETUB (97% identical), macaque FETUB (82% identical), dog FETUB (69% identical), rabbit FETUB (67% identical), mouse Fetub (64% identical), rat Fetub (62% identical), pig FETUB (59% identical), guinea pig FETUB (54% identical), zebrafish fetub (31% identical), tropical clawed frog fetub (30% identical), zebrafish si:ch211-284e20.8 (22% identical). Paralogues in human: HRG (24% identical), AHSG (20% identical), KNG1 (19% identical).
Diseases named in the same sentence as FETUB in open-access papers:
FETUB is named in the same sentence as 60 diseases in open-access papers, as found by Europe PMC text mining. Sharing a sentence is not in itself a finding about the gene and the disease. The quoted sentences say what the papers report.
Insulin resistance (23 papers, 2017 to 2025). Increased resistance towards insulin, that is, diminished effectiveness of insulin in reducing blood glucose levels. "Fetuin-B is a relatively understudied hepatokine associated with insulin resistance, dyslipidemia, and non-alcoholic fatty liver disease." (PMID 36416543, 2023). "To verify the effect of Fetuin B on the association between leptin and insulin resistance, we performed mediation analysis in a population with central obesity." (PMID 35896788, 2022). "Here, our objective is to investigate the changes in circulating Fetuin-B levels in women with polycystic ovary syndrome (PCOS) and analyze the association of Fetuin-B and insulin resistance (IR)." (PMID 33061822, 2020). "In humans, plasma fetuin B levels are increased in obese individuals with hepatic steatosis and T2D, and associated positively with intrahepatic triglyceride and insulin resistance." (PMID 31736870, 2019). "Fetuin B has also been reported to be up-regulated in obese mice, and associated with the development of insulin resistance/type 2 diabetes and hepatic steatosis." (PMID 31258482, 2019). "Although both hepatic-secreted proteins are positively associated with hepatic steatosis, insulin resistance, and diabetes, the fetuin-B mechanism of action is different from AHSG, which acts as an inhibitor of insulin receptors." (PMID 30395577, 2018). "We used Mendelian randomization analysis by incorporating information of genetic variants in FETUB and serum fetuin-B concentrations with insulin resistance in 1148 obese Chinese adults." (PMID 29390354, 2017). "Higher serum fetuin-B levels were significantly associated with increased homeostasis model assessment of insulin resistance (HOMA-IR) (0.17 [95%CI: 0.01 to 0.32, P = .037] 10−6 mol IU L−2 higher per SD)." (PMID 29390354, 2017). "For example, fetuin-B is correlated with severity of hepatic steatosis which itself is also independently associated with insulin resistance." (PMID 29390354, 2017). "Fetuin-A has been found to cause insulin resistance, but the role of fetuin-B in the pathogenesis of insulin resistance has been seldom investigated after its identification." (PMID 29390354, 2017). "So for future studies on the possible causal relationship between fetuin-B and insulin resistance using MR analysis, more genetic variants, including both common and rare SNPs, should be included as the instrumental variables." (PMID 29390354, 2017). "The aim of this study was to explore the potential causal relationship between fetuin-B and insulin resistance." (PMID 29390354, 2017). "We firstly confirmed that increased serum fetuin-B level was significantly associated with higher risk of insulin resistance." (PMID 29390354, 2017). "The present study, to the best of our knowledge, is the first to examine the association between fetuin-B and insulin resistance using MR analysis." (PMID 29390354, 2017). "The results of mediation analysis showed that hyperleptinemia could induce insulin resistance, and Fetuin B partially mediated the increase in insulin resistance caused by leptin." (PMID 35896788, 2022). "Although our data mostly reflect associations, it is tempting to speculate that elevated Fetuin-B levels represent a novel mechanism supporting adipose insulin resistance found in subjects with obesity and increased liver fat." (PMID 34611132, 2021). "Even if the cellular structures potentially underlying such an interaction of Fetuin-B and adipose insulin resistance are currently unknown, this adds relevant novel aspects to existing knowledge." (PMID 34611132, 2021). "Weight loss induced improvements of insulin resistance were almost completely preserved until months 12 and 18 and most interestingly, the short and long-term improvement of FFASupp was partially predicted by baseline level of Fetuin-B." (PMID 34611132, 2021). "Elevated serum fetuin-B is suggested to be associated with insulin resistance, but it is unknown if this association is causal." (PMID 29390354, 2017).
Insulin resistance (continued). "In the present study, by incorporating all information of common genetic variants in the FETUB locus and serum fetuin-B concentrations with insulin resistance, we aimed to explore the potential causal relationship between fetuin-B and insulin resistance in obese Chinese adults by suing MR analysis." (PMID 29390354, 2017). "Although we found that the elevated serum fetuin-B concentration was significantly associated with increased risk of insulin resistance, results from MR analysis suggested that this association may not be causal." (PMID 29390354, 2017). "Future studies on the nongenetic determinants of serum fetuin-B concentration to assess if such unmeasured factors may confound the association between fetuin-B and insulin resistance as well as more pathway analysis for this association are warranted." (PMID 29390354, 2017). "By using the genetic variants of FETUB SNPs as instrumental variables to assess the potential causality of fetuin-B with insulin resistance, we found that the associations of measured fetuin-B and genetically predicted fetuin-B with HOMA-IR were significantly different." (PMID 29390354, 2017). "Our previous data also suggest an independent association between serum fetuin-B and insulin resistance, but whether fetuin-B is causally related to insulin resistance is currently unknown." (PMID 29390354, 2017). "Associations of FETUB genotypes and minor allele, serum fetuin-B levels with insulin resistance." (PMID 29390354, 2017). "First, our subjects were all obese, and we may underestimate the association between serum fetuin-B and insulin resistance." (PMID 29390354, 2017). "Therefore, we cannot exclude the possibility that some rare SNPs among the FETUB locus are associated with insulin resistance and may underestimate the true association between genetically predicted fetuin-B levels and HOMA-IR." (PMID 29390354, 2017). "Serum fetuin-B levels are increased in PCOS patients and have been linked to insulin resistance and NAFLD." (PMID 40636369, 2025). "Elevated serum fetuin B in PCOS patients.Fetuin B plays a role in the development of insulin resistance; however, the mechanism is not fully understood." (PMID 39858445, 2025). "Especially observed at high levels in MASLD, fetuin-B aggravates insulin resistance by blocking AMPK and activating the LXR-SREBP1c axis, hence fostering hepatic lipogenesis." (PMID 40868109, 2025). "Beyond PCOS, elevated fetuin-B levels have also been linked to metabolic disorders, including type 2 diabetes, gestational diabetes, NAFLD, and insulin resistance, all of which are conditions that often co-occur with PCOS." (PMID 40636369, 2025). "Fetuin-B levels are known to be elevated in PCOS patients and have been linked to adverse metabolic outcomes, including insulin resistance and increased risk of NAFLD." (PMID 40636369, 2025). "Fetuin B has been revealed as a hepatokine that is involved in regulating metabolic homeostasis and insulin resistance." (PMID 35896788, 2022). "The hepatokine Fetuin B participates in regulating insulin resistance, glucose metabolism and liver steatosis." (PMID 35896788, 2022). "Given this evidence, it is rational to propose that Fetuin B, a hepatokine involved in regulating insulin resistance and metabolism, is transcriptionally regulated by leptin released from adipose tissues." (PMID 35896788, 2022). "Emerging evidence from human studies has also demonstrated that circulating Fetuin-B levels are upregulated in patients with NAFLD, which are closely associated with insulin resistance." (PMID 34944728, 2021). "Taken together, we revealed a novel relationship of Fetuin-B to several markers of insulin resistance, especially estimates of adipose tissue function." (PMID 34611132, 2021). "Nevertheless, based on the findings from a number of studies, Fetuin-B is another potential therapeutic target in the treatment of metabolic diseases, such as obesity and insulin resistance." (PMID 34944728, 2021).
Insulin resistance (continued). "Elevated levels of fetuin-B, translated by the FETUB gene, have been described as associated with insulin resistance." (PMID 32590936, 2020). "Our findings are in agreement with other data focused on the relationships between serum fetuin-B concentration and different states of insulin resistance." (PMID 31307012, 2019). "The aim of the study was to evaluate the relationships between serum fetuin-B concentration and indices of insulin resistance, insulin secretion and markers of liver steatosis in PCOS women in comparison to the control group." (PMID 31307012, 2019). "In our study, we observed higher serum fetuin-B concentration and FLI as well as a relationship between serum fetuin-B concentration and different indices of liver steatosis and insulin resistance in PCOS women." (PMID 31307012, 2019). "Fetuin-B appears to be a hepatokine that becomes dysregulated in hepatic steatosis and insulin resistance." (PMID 31307012, 2019). "Studies have reported increased serum fetuin B in PCOS patients, with the suggestion that fetuin B could be a factor associated with NAFLD in PCOS through enhancing insulin resistance." (PMID 39858445, 2025). "Therefore, Fetuin B is closely correlated with insulin resistance and potentially mediates obesity-related metabolic disorders." (PMID 35896788, 2022). "Moreover, the biological function of Fetuin B in promoting insulin resistance and glucose intolerance was consistent with the detrimental effects of leptin in the liver, as defined in aged or obese models." (PMID 35896788, 2022). "Finally, the mediating effect of Fetuin B in insulin resistance induced by leptin was confirmed according to mediation analysis in this obese population." (PMID 35896788, 2022). "Interestingly, Fetuin-B levels were associated with estimates of obesity, liver steatosis (HSI), and insulin resistance (high HOMA-IR, low ISIClamp, and weaker insulin-mediated suppression of FFAs (FFASupp))." (PMID 34611132, 2021). "Furthermore, the plasma concentration of Fetuin-B significantly correlated with clinical indices of obesity, hepatic steatosis, and homeostatic model assessment for insulin resistance." (PMID 34944728, 2021). "Recent cell-based studies revealed that Fetuin-B induces insulin resistance in cultured hepatocytes, as well as myotubes and promotes lipid accumulation in HepG2 cells presumably via its capacity for decreasing AMPK activity, while activating liver-X-receptor α-SREBP-1c signaling." (PMID 34944728, 2021). "Cell-based studies have demonstrated that fetuin B can lead to insulin resistance in myotubes and hepatocytes, and in vivo studies have shown that administration of fetuin B to lean mice causes glucose intolerance but not insulin resistance." (PMID 31736870, 2019). "Therefore, the aim of the present study was to evaluate the relationships of serum fetuin-B concentration with indices of insulin resistance and insulin secretion, and with markers of liver steatosis in PCOS women in comparison to the control group." (PMID 31307012, 2019). "The authors concluded that fetuin-B links NAFLD to T2D via inducing insulin resistance." (PMID 31307012, 2019). "In mice, they found fetuin-B impaired significantly glucose tolerance but did not cause insulin resistance." (PMID 29390354, 2017). "Common genetic variants (FETUB rs4686434, rs6785067, and rs3733159) were significantly associated with serum fetuin-B concentrations but not with insulin resistance." (PMID 29390354, 2017). "Furthermore, fetuin-B establishes a metabolic feedback loop in adipocytes by interacting with the insulin receptor-β, therefore sustaining the interaction between hepatic steatosis and peripheral insulin resistance." (PMID 40868109, 2025). "Furthermore, fetuin B induces a pro inflammatory response in adipocytes, and could mediate peripheral insulin resistance, which could lead to NAFLD." (PMID 41341131, 2025).
Insulin resistance (continued). "Future studies on the nongenetic determinants of serum fetuin-B concentration to assess if such unmeasured factors in the present study may confound the association between fetuin-B and insulin resistance are needed." (PMID 29390354, 2017). "The third explanation is that the observed association between serum fetuin-B concentrations and insulin resistance may be confounded by other determinants of fetuin-B and meanwhile FETUB SNP variants are not confounded by the same determinants." (PMID 29390354, 2017). "Based on the relationship between HOMA-IR, FFASupp, and Fetuin-B levels at baseline and during weight loss, we wondered if baseline Fetuin-B may be also predictive for weight loss-induced improvement of these estimates of insulin resistance, independent of body weight reduction." (PMID 34611132, 2021). "In humans, plasma levels of fetuin-B are elevated in obese people with fatty liver and DM2, and studies have shown that steatosis is more closely related to the development of insulin resistance than obesity itself." (PMID 33807959, 2021). "This study suggests the association between fetuin-B and insulin resistance may not be causal." (PMID 29390354, 2017). "Therefore, we could not exclude the possibility that the association of serum fetuin-B with insulin resistance is through other different mechanisms, and more pathway analysis for this association is warranted." (PMID 29390354, 2017). "Six proteins function in regulating glucose homeostasis, insulin resistance, and β-cell function, including SHBG, FETUB, PRG4, GSN, CFD, and TF, among which SHBG and FETUB are markers of insulin sensitivity and the expression of TF in adipose tissue is positively associated with insulin sensitivity." (PMID 38182717, 2024). "As it was mentioned in the Introduction section, it has been shown that serum fetuin-B is increased in NAFLD and may be connected with insulin resistance." (PMID 31307012, 2019). "Serum fetuin-B concentrations in subjects with insulin resistance were significantly higher than those without it (P = .004)." (PMID 29390354, 2017). "Therefore, the association between fetuin-B and insulin resistance may not be causal." (PMID 29390354, 2017). "Therefore, based on our results, it might be suggested that fetuin-B could be one of the factors connected with NAFLD in PCOS women, probably by enhancing insulin resistance." (PMID 31307012, 2019).